YWHAZP5 (tyrosine 3-monooxygenase/tryptophan 5-monooxygenase activation protein zeta pseudogene 5)
Gene: Processed pseudogene on chromosome 10 (105,686,322 to 105,687,051, forward strand). Ensembl gene ENSG00000213260.
Diseases named in the same sentence as YWHAZP5 in open-access papers:
YWHAZP5 is named in the same sentence as 7 diseases in open-access papers, as found by Europe PMC text mining. Sharing a sentence is not in itself a finding about the gene and the disease. The quoted sentences say what the papers report.
Intellectual disability (1 paper, 2024). "Similar to the YWHAZ phenotype, the chromosomal regions harboring YWHAZP4 (6q22.33), YWHAZP5 (10q25.1), YWHAZP6 (9p13.3), YWHAZP8 (Xq13.2), and YWHAZP10 (Xp11.4) are associated with intellectual disability." (PMID 38674334, 2024).
psoriatic arthritis (1 paper, 2024). Joint inflammation associated with psoriasis. "A study of T cells from the blood and synovial fluid of psoriatic arthritis patients revealed the expression of YWHAZP3 and YWHAZP10 in both leukocytes and T cells; the expression of YWHAZP1, YWHAZP5, and YWHAZP6 in leukocytes only; the expression of YWHAZP2 in T Cells only." (PMID 38674334, 2024).
schizophrenia (1 paper, 2015). A major psychotic disorder characterized by abnormalities in the perception or expression of reality. "The results showed that variants near one gene, which encodes YWHAZP5, were most significantly associated with working memory deficits in schizophrenia patients." (PMID 25608650, 2015).
YWHAZP5 also shares sentences with these, for which no sentence is quoted: autoimmune thrombocytopenia (1 paper); immune thrombocytopenia (1); juvenile idiopathic arthritis (1); rheumatoid arthritis (1).